MGMT (O-6-methylguanine-DNA methyltransferase)
Diseases named in the same sentence as MGMT in open-access papers (continued):
Sharing a sentence is not in itself a finding about the gene and the disease.
tumor (continued). "Taken together, the data demonstrated that tumor stage 3, moderately differentiated tumors, presence of lymphatic invasion and absence of metastasis were more frequently observed in tumors with mutated Kras and methylated RASSF1A, FHIT and MGMT genes." (PMID 23573237, 2013). "The most attractive use of PARP inhibitors might be in those patients whose tumour is MGMT-unmethylated and currently derive less benefit from chemo-radiotherapy." (PMID 23510353, 2013). "Patients with significantly different OS could even be identified among those with known good prognosis (methylated MGMT promoter-bearing tumor) using Agilent (OS 25 versus 8.1 months; p < 0.01) and RT-PCR (OS 21.8 versus 13.9 months; p < 0.05) technologies." (PMID 22980038, 2012). "Mice overexpressing MGMT are more resistant to toxicity and tumor induction by alkylating agents." (PMID 23300791, 2012). "The observed demethylating effect of 5-Aza on the proliferative activity of UM-SCC 33 tumor cell line cannot be attributed only to demethylation of MGMT and RASSF1A promoter, since further hypermethylated TSGs might also be involved." (PMID 22246327, 2012). "In addition, we compared MGMT related parameters with those of volumetry in order to observe possible implications of this molecule in tumor development and, subsequently, treatment response." (PMID 22214427, 2012). "Finally, tumors with MGMT methylation had a mean tumor size of 3.2 cm, which was significantly larger compared with tumors without MGMT methylation (2.1 cm; P = 0.002)." (PMID 22765268, 2012). "The intracellular level of MGMT varies among tumours of the same histological type." (PMID 22264301, 2012). "Finally, both an increase and a decrease in MGMT expression have also been described for recurrent tumours." (PMID 21269507, 2011). "MGMT mRNA expression plays a direct role for mediating tumor sensitivity toalkylating agents." (PMID 21365007, 2011). "Overexpression of MGMT has an important role in tumour resistance to chemotherapy." (PMID 21811257, 2011). "A nearly identical frequency of concordant and discordantfindings was obtained by analyzing the TCGA database (p<0.0001).Expression of DNMT1 and DNMT3b was strongly upregulated in tumor tissue, butnot correlated with MGMT promoter methylation and MGMT mRNAexpression." (PMID 21365007, 2011). "Thus, MGMT confers resistance to alkylating agents in a wide spectrum of human tumours by reversing DNA toxicity." (PMID 21269507, 2011). "Thus, depletion of MGMT activity in these tumours should result in enhanced sensitivity to temozolomide." (PMID 20628383, 2010). "The MGMT methylation status of the tumour could therefore be more a patient phenotype having little to do with MGMT expression level and TMZ chemoresistance." (PMID 20736948, 2010). "Interestingly, we found an effect of MGMT promoter methylation status of the tumour biopsy on patients’ tolerance of TMZ." (PMID 20736948, 2010). "However, just 1 week after treatment with 21 days of temozolomide on the dose-intense schedule, tumour MGMT activity had returned to pretreatment levels." (PMID 20628383, 2010). "On day 6, MGMT activity in tumour remained suppressed in both groups." (PMID 20628383, 2010). "For the next set of experiments, we sought to determine whether the more prolonged depletion of MGMT activity using the dose-intense temozolomide schedule translated into improved tumour control and survival." (PMID 20628383, 2010). "As EGFR, PTEN and MGMT genes are usually altered in primary GBMs, we decided to corroborate the primary nature of our samples by checking for the existence of these alterations in the bulk tumour cell population of GBMs by FISH analysis and MLPA assay." (PMID 20735813, 2010). "We used this sequential regimen to verify the hypothesis that continuous exposure to alkilating agent TMZ could effectively deplete tumoral cells of MGMT which is the primary mechanism of tumor resistance to nitrosureas." (PMID 21067582, 2010).
tumor (continued). "However, by day 29, 1 week after the completion of treatment on schedule B, tumour MGMT activity had returned to pretreatment levels." (PMID 20628383, 2010). "Tumour MGMT activity was depleted by day 6 in both treatment groups compared with baseline." (PMID 20628383, 2010). "In this respect, immunohistochemistry, determining the expression of the MGMT protein per individual cell, may be a better technique for screening human tumour samples." (PMID 20517307, 2010). "Interestingly, these authors found a significant correlation for methylation of different genes, including MGMT, between tumor pairs of the same site (proximal vs. distal)." (PMID 20098741, 2010). "Owing to the mechanism by which MGMT repairs O6-methylguanine adducts and is subsequently degraded, the use of alternative dosing regimens is an appealing method to enhance temzolomide mediated tumour cytotoxicity." (PMID 20628383, 2010). "Second, of the 8 tumors for which MGMT promoter analysis could be performed, 7 (87.5%) were unmethylated, a known factor of overall tumor resistance against alkylating agent therapy." (PMID 19840379, 2009). "The low cell-doubling rate in patients' tumours and the observed rapid recovery of MGMT activity suggest repair of O6-MeG may well precede two rounds of DNA replication, in contrast to the situation in cell culture and tumour xenograft models." (PMID 19367283, 2009). "For this reason, the role of MGMT should be further assessed prospectively in a larger cohort of patients undergoing fotemustine chemotherapy, possibly re-assessing MGMT status at the time of tumor recurrence." (PMID 19335893, 2009). "The inactivation of MGMT might thus be expected to increase the toxic effects of chemotherapy in tumours to a greater extent than in the bone marrow, and hence improve the therapeutic index." (PMID 19367283, 2009). "O6-methylguanine is toxic only through replication and may be repaired effectively at any point beforehand, so one possible explanation was that the recovery of tumour MGMT levels occurred before successive rounds of replication could cause cell death." (PMID 19367282, 2009). "High levels of endogenous MGMT in tumor cells are believed to protect the tumor from alkylating agents used in chemotherapeutic regimen and MGMT levels may be an important parameter of treatment failure." (PMID 19274096, 2009). "In the later study, MGMT promoter methylation was an independent favourable prognostic factor and patients whose tumour contained a methylated MGMT promoter had median survival of 21.7 months and 2-year survival of 46%, when treated with temozolomide and radiotherapy." (PMID 19536096, 2009). "However, we found residual MGMT activity in the majority of tumour biopsies taken at later times after the end of the first LM/TMZ cycle, even when the daily dose of LM was increased." (PMID 19367283, 2009). "MGMT promoter methylation analysis, assessed in all tumors at the time of initial resection, provided unequivocal results in 8 patients, and demonstrated a promoter methylation in only one tumor (patient # 3)." (PMID 19840379, 2009). "Total MGMT protein was determined in 15 tumour biopsies taken following LM/TMZ." (PMID 19367283, 2009). "This supports the hypothesis that MGMT inactivation by aberrant promoter methylation correlates with the sensitivity of the tumor to alkylating agents." (PMID 19274096, 2009). "Sections were taken from a single block of tissue that had either no, clonal, or complete loss of MGMT expression in the tumor cells." (PMID 19393074, 2009). "MGMT was most frequently methylated in both tumour histotypes, that is in 92% of all carcinomas." (PMID 17971771, 2007). "It is speculated that although the tumor was initially resistant to TMZ monotherapy because of positive MGMT protein expression, the interferon-beta suppressed MGMT expression by the tumor, thus rendering it sensitive to interferon-TMZ combination treatment." (PMID 17683572, 2007).
tumor (continued). "Several tumour types have also shown aberrant methylation at the CpG island in other genes, including the FAP-associated gene APC, detoxifying gene GSTP1, DNA repair gene MGMT, the potential metastasis inhibitor gene DAP-kinase, and Rb interact gene RIZ1." (PMID 17968429, 2007). "Based on these considerations it would be interesting to conduct a prospective trial studying MGMT expression in blood and tumour samples in order to understand the activity of temozolomide and its toxicity profile as this would be conducive to personalising drug delivery." (PMID 17024124, 2006). "Nevertheless, to address the questions of MGMT inactivation by cisplatin in relation to tumour responses and toxicities, it would be necessary to undertake larger studies, ideally in direct comparison with equivalent numbers of patients receiving temozolomide alone." (PMID 16136028, 2005). "Tumour resistance to chemotherapy involving methylating agents such as DTIC (dacarbazine) and temozolomide is linked to expression of the DNA repair protein O6-alkylguanine-DNA alkyltransferase (MGMT)." (PMID 16278661, 2005). "In addition, preclinical studies suggested that cisplatin can attenuate the expression of MGMT resulting in increased sensitivity to temozolomide and additive tumour growth inhibition." (PMID 16136028, 2005). "Strategies have therefore focussed on the use of nontoxic MGMT inactivators and it has been shown that O6-BeG and PaTrin-2, which very effectively inactivate MGMT in cells and tumours, improve the therapeutic effect of alkylating agents in a number of tumour models." (PMID 16278661, 2005). "The heterogeneity between and within tumours from the same patient may be due to tumour cell subpopulations with differences in MGMT expression, possibly related to heterogeneity in MGMT promoter methylation." (PMID 14562026, 2003). "A future approach to treatment of tumours with high expression of MGMT may consist of depletion of tumour MGMT with O6-BG and protection of sensitive bone marrow cells, using genetic modification with O6-BG-resistant MGMT mutants, such as P140 K and G156A." (PMID 14562026, 2003). "Furthermore in tumours showing both MGMT expression and promoter methylation, three cases showed loss of expression in the focal area of the tumour, i.e., 1 or 2 glands in intestinal type or a small area in diffuse type." (PMID 12085181, 2002). "In 33 patients in whom MGMT level and clinical response could be evaluated, the tumour MGMT levels (fmol mg(-1) protein) were: CR, 158 +/- 119; PR, 607 +/- 481; NC, 171 +/- 101; PD, 185 +/- 42.3." (PMID 9820180, 1998). "It is important to note that peritumoral edema represents a downstream effect of a tumor, and may not be directly linked to expression of MGMT." (PMID 41476598, 2025). "In addition, a low MGMT score (≤50) was found as a good cutoff to predict tumor response." (PMID 40438391, 2025). "In addition, most studies have focused exclusively on the intratumoral area despite growing evidence that the pre-tumoral microenvironment carries valuable information reflecting tumor infiltration, edema, and microvascular remodeling related to MGMT promoter methylation." (PMID 41584616, 2025). "Co-delivery of complementary agents—such as anti-angiogenic drugs (e.g., bevacizumab), immune checkpoint inhibitors (e.g., anti-PD-1/PD-L1 antibodies), or gene-silencing molecules (e.g., siRNAs targeting MGMT or VEGF)—could synergistically target multiple components of the tumor microenvironment." (PMID 40678580, 2025). "Additionally, other studies found no predictive ability of MGMT promoter methylation in peritumoral edema, but it is concluded that the edema volume could impact survival if the tumor is MGMT methylated." (PMID 41476598, 2025).
tumor (continued). "However, none of the mice implanted with MGMT KO cells showed any symptoms of a tumor, such as weight loss and hunching." (PMID 40336841, 2025). "The total tumor/edema ratio was significantly lower in MGMT methylated group from both DeepBraTumIA (0.417, Std 0.062) and Raidionics (0.332, Std 0.048) segmentations compared to non MGMT methylated [DeepBraTumIA (0.876, Std 0.213) and Raidionics (0.747, Std 0.120)]." (PMID 41476598, 2025). "The improved therapeutic outcome observed with the combination of temozolomide and capecitabine may be due to its ability to decrease O6-methylguanine DNA methyltransferase (MGMT) levels in tumor cells, thereby boosting the alkylating effectiveness of temozolomide." (PMID 41375037, 2025). "Therefore, we believe that the transcription of the MGMT promoter could be blocked by inhibiting the ERK pathway to reduce the level of MGMT protein, thus antagonising the drug resistance of tumour cells to TMZ." (PMID 39873425, 2025). "This demonstrates the insufficiency of using MGMT methylation status or gene expression directly as a biomarker in clinics, and underpins the necessity of our computational models using molecular profiling data generated from functional tumor cell screening project." (PMID 39763506, 2025). "Overall, these findings suggest that MGMT methylation is associated with improved survival but an increased risk of out-field recurrence, while EGFR amplification is linked to higher rates of marginal recurrence, potentially reflecting a more invasive tumor phenotype." (PMID 40722305, 2025). "This suggests that the methylation pattern of MGMT may vary depending on tumor grading." (PMID 41153666, 2025). "Thus, patient stratification by a tumor’s MGMT status may be critical when combining methylating agents with IFN agonists, which carry their own risks." (PMID 41256671, 2025). "We therefore directly genotyped the tumour samples of the AGO-OVAR 11 study for the most strongly associated variants in CABLES1 (rs77770767, rs28589524, rs6507532, rs4281829), PPP2R5C (rs2448233, rs59784377, rs3783362, rs79999043), FAM35A (rs11492866) as well as for the MGMT variant rs72845444." (PMID 38443389, 2024). "Interestingly, patients with surgically removed GBM treated with temozolomide showed a longer overall survival if the resected tumor had low levels of mGlu3 transcript, and the methylation state of the MGMT gene promoter influenced survival only in patients with low mGlu3 receptor mRNA in the tumor." (PMID 38509672, 2024). "Importantly, MGMT was overexpressed in the post-treatment tumour (E169-M2)." (PMID 38978571, 2024). "Since MGMT promoter methylation status plays a critical role during the priming phase of this trial, it is essential to select and validate a sensitive and specific method for methylation analysis in order to minimize issues related to sampling and tumor heterogeneity." (PMID 39594133, 2024). "Therefore, further prospective research on a more representative population is warranted to establish possible relationships between kinin receptor expression and other tumor molecular features, such as IDH mutation status, EGFR amplification, PTEN deletions/mutations, and MGMT methylation status." (PMID 38254732, 2024). "Additionally, given the variety of methods currently in use for assessing MGMT promoter methylation, which often give disparate results, the optimal method and cut off for classifying tumours as MGMT promoter methylated or unmethylated remains unknown." (PMID 38500668, 2024). "Furthermore, we observed a correlation between elevated MRM score and malignancy features characterized by older age, mortality, absence of IDH1 mutation, higher tumor grading, lack of 1p19q co-deletion, and MGMT promoter methylation." (PMID 38824202, 2024).
tumor (continued). "MMR mutations occurring after TMZ administration may occur either through the selection of MMR-deficient subclones already present in the heterogeneous tumor cell population or by TMZ directly inducing mutation in an MMR gene, particularly in tumor cells with methylated MGMT." (PMID 39012509, 2024). "The urgent need for new treatments for GBM that may come from drug repurposing is shown by the fact that TMZ only increased median survival by 2 months, MGMT promoter unmethylated patients are much less sensitive to the drug, and rapid tumor recurrence often occurs." (PMID 38531616, 2024). "Given that the G-CIMP is highly enriched in IDH1-mutant proneural GBM, as well as the positive association between MGMT methylation and G-CIMP in GBM tumours, the role of IDH1 mutations in MGMT silencing may be related to IDH-mutant-induced histone methylation." (PMID 38615034, 2024). "Emerging data suggests that temozolomide chemotherapy may be a viable alternative to radiation therapy for older patients with MGMT-methylated tumours who cannot benefit from a combined-modality approach due to poor functional status or significant comorbidity." (PMID 39099691, 2024). "The influence of MGMT promoter methylation on treatment response introduces further variability, as metformin’s effectiveness could differ significantly between methylated and unmethylated tumor subtypes." (PMID 38891882, 2024). "Patients with high MRM score had a poor clinical outcome, which may be associated with that IDH1 wild-type, high grade tumor, 1p19q non-codeletion, and MGMT promoter nonmethylation were enriched in high MRM score." (PMID 38824202, 2024). "Further studies on MGMT promoter methylation in subtypes of pediatric diffuse high-grade gliomas may be warranted to explore the link between the degree of MGMT promoter methylation within pHGG tumor types and post-treatment hypermutation." (PMID 37670377, 2023). "However, additional MGMT-independent mechanisms have also been linked to TMZ resistance and tumour heterogeneity and genetic alterations are assumed to be further reasons for tumour recurrence and treatment failures." (PMID 37907716, 2023). "Moreover, the base excision repair pathway is a parallel process of alkylator repair and preliminary studies suggest that TMZ in combination with PARP inhibitors (PARPi) may enhance tumor cell death in MGMT-silenced tumors." (PMID 37387791, 2023). "Thus, if tumor cellularity is too low in a specimen, with too many admixed non-neoplastic cells (including astrocytes, neurons, inflammatory cells, etc.), MGMT promoter methylation signals could be diluted, leading to a false-negative result." (PMID 37919784, 2023). "Moreover, we will try to identify those miRNAs that might be potential regulators of MGMT expression and their role as predictors of tumor response to temozolomide treatment." (PMID 37371047, 2023). "In addition, not all tumours are responsive to temozolomide chemotherapy, and some patients’ tumours may express the enzyme O6-methylguanine-DNA-methyltransferase (MGMT)." (PMID 37626597, 2023). "The main evidence emerging from this study is that IPA and its analog N6-BA could influence the expression of methylated genes involved in tumor-related mechanisms, such as MGMT, FBXW7, and potentially others, suggesting the existence of an epigenetic regulation behind their pleiotropic actions." (PMID 35559231, 2022). "Patients with unmethylated MGMT-promoter and IDH WT markers received a vaccination with autologous dendritic cells loaded with mRNA-encoding hTERT (telomerase) and survivin, both overexpressed antigens in GBM and tumour stem cell mRNA from autologous tumour spheres." (PMID 35454848, 2022).